RALA (RAS like proto-oncogene A)
Diseases named in the same sentence as RALA in open-access papers (continued):
Sharing a sentence is not in itself a finding about the gene and the disease.
Arterial thrombosis (1 paper, 2025). The formation of a blood clot inside an artery. "Genetic deletion of Ral GTPases, RalA and RalB, conditionally in mouse platelets (RalAB double knockout [DKO]), results in a near complete defect in P-selectin externalization upon activation, while other platelet activation responses and arterial thrombosis are preserved." (PMID 39454881, 2025).
astrocytoma (1 paper, 2022). "Furthermore, the transcriptional expression of RalA also augments in GBMs versus astrocytoma, although to a lesser extent." (PMID 35897776, 2022). "In accordance with this, we observed RalA protein level increases in 4 out of 10 primary GBM samples, compared to astrocytoma samples." (PMID 35897776, 2022). "First, we have analyzed the expression levels of RalA and RalB proteins in primary cultures obtained from human GBM and grade II astrocytoma biopsies." (PMID 35897776, 2022).
benign prostatic hyperplasia (1 paper, 2016). A non-cancerous nodular enlargement of the prostate gland. "In the present study, we used recombinant RalA as a target autoantigen, and evaluated its immunoreactivity by ELISA and Western blotting in sera from patients with PCa and benign prostatic hyperplasia (BPH), and in normal human sera (NHS)." (PMID 27286458, 2016).
bladder tumor (1 paper, 2022). "Note that the knock-out of either RalA or RalB does not affect the growth of mouse embryonic fibroblasts (MEFs), and slightly reduces the growth of some cancer cells, such as bladder tumor cells, when growing in low-serum conditions." (PMID 35897776, 2022).
bone metastasis (1 paper, 2019). Transfer of a neoplasm from its primary site to bones. "MAZ expression was elevated in PCa tissues with bone metastasis (T4–6) compared with expression in PCa tissues without bone metastasis and was further increased in metastatic bone tissues (T7–9); consistently, protein expression of KRas and activated RalA exhibited the same pattern." (PMID 31488180, 2019).
breast tumor (1 paper, 2018). "In this work we examined Ral protein expression in patient breast tumor samples and we found overexpression of both RalA and RalB as compared to normal breast tissues, therefore adding breast cancers to the list of human cancers with potential overstimulation of Ral pathway." (PMID 30320548, 2018).
cancers of the liver (1 paper, 2017). "Our team has demonstrated the overactivation of the RalA signaling pathway in a number of human malignancies including cancers of the liver, ovary, lung, brain, and malignant peripheral nerve sheath tumors." (PMID 29047224, 2017).
cardiomyopathy (1 paper, 2022). A disease of the heart muscle or myocardium proper. "We next sought to find out whether elevation of the GDP-bound form of RalA might be of therapeutic value for treatment of pressure overload-induced cardiomyopathy." (PMID 35879328, 2022).
Costello syndrome (1 paper, 2018). Costello syndrome (CS) is a rare multisystemic disorder characterized by failure to thrive, short stature, developmental delay or intellectual disability, joint laxity, soft skin, and distinctive facial features. "Lastly, a de novo HRAS variant at Ala146, the homologous equivalent of Ala158 in RALA, was reported in at least three patients with Costello Syndrome." (PMID 30500825, 2018). "A de novo variant in HRAS at Lys117, the homologous equivalent of Lys128 in RALA, was found in two unrelated probands with Costello Syndrome." (PMID 30500825, 2018).
developmental disability (1 paper, 2018). Disorders in which there is a delay in development based on that expected for a given age level or stage of development. "Together, we have provided evidence that genetic changes in RALA can cause developmental disabilities." (PMID 30500825, 2018).
diabetes mellitus (1 paper, 2009). A metabolic disorder characterized by abnormally high blood sugar levels due to diminished production of insulin or insulin resistance/desensitization. "Moreover, in addition to its role in the regulation of insulin release it will be important to define the possible involvement of RalA in other β-cell functions that when deregulated favour the development of diabetes mellitus such as apoptosis or proliferation." (PMID 19890390, 2009).
empty sella (1 paper, 2025). "Additionally, previously unreported neuroradiological findings such as partial empty sella in case 1 and ventricular enlargement in case 2 may contribute to expand the phenotypic spectrum associated with RALA variants." (PMID 39918382, 2025).
in situ carcinoma (1 paper, 2018). A malignant epithelial neoplasm which is confined to the epithelial layer without evidence of further tissue invasion. "(B) Quantitative analysis of RalA protein level in patient samples of normal juxtatumural tissue (n = 371), in situ carcinoma (n = 144), invasive ductal carcinoma (n = 462) and lymph node metastasis (n = 87)." (PMID 30320548, 2018).
invasive ductal carcinoma (1 paper, 2018). "In invasive ductal carcinoma, RalB protein expression was slightly higher in luminal A and B than in HER2 +and triple-negative (TN) tumors, while RalA protein expression was slightly lower in TN tumors as compared to the other subtypes." (PMID 30320548, 2018).
leukemia (1 paper, 2023). A malignant (clonal) hematologic disorder, involving hematopoietic stem cells and characterized by the presence of primitive or atypical myeloid or lymphoid cells in the bone marrow and the blood. "GFP+ (BCR-ABL-expressing leukemia cells) populations in BM increased significantly in the RalA Rosa26-Tg/+ group." (PMID 36923939, 2023). "Collectively, RalA was detected to be a vital factor that regulates the abilities of HSCs and LSCs, thus facilitating BCR-ABL-triggered leukemia in mice." (PMID 36923939, 2023).
medulloblastoma (1 paper, 2017). A malignant, invasive embryonal neoplasm arising from the cerebellum. "Our recent unpublished work shows that RalA is overactivated in glioma and medulloblastomas, which makes them promising targets for reovirus therapy." (PMID 29047224, 2017). "Finally, medulloblastoma CD133+ cells were also found to contain higher levels of RalA activation." (PMID 29047224, 2017).
metastatic prostate carcinoma (1 paper, 2018). A carcinoma that arises from the prostate gland and has spread to other anatomic sites. "There is also a clear anti-cancer effect of RALA/iNOS gene therapy for metastatic prostate cancer following both in vitro and in vivo studies." (PMID 29899810, 2018).
multiple myeloma (1 paper, 2022). "In the early studies of multiple myeloma (MM), experiments had shown that RALB can promote the migration of OPM-1 and NCI-H929 cells, but RALA did not have this effect." (PMID 36466919, 2022).
Noonan syndrome (1 paper, 2018). Noonan Syndrome (NS) is characterized by short stature, typical facial dysmorphism and congenital heart defects. "De novo heterozygous missense variation at Val14 of KRAS, the homologous equivalent of Val25 in RALA, was previously reported in four unrelated individuals with Noonan syndrome." (PMID 30500825, 2018).
oral squamous cell carcinoma (1 paper, 2022). "A study in oral squamous cell carcinoma showed that RALGAPB silencing increased the level of RalA activation, promoting HSC-2 cell migration and invasion in vitro, a profile characteristic of metastatic cells." (PMID 36412911, 2022).
pulmonary hypertension (1 paper, 2023). Increased pressure within the pulmonary circulation due to lung or heart disorder. "A total of 15 patients without pulmonary hypertension (non-PAH), 19 patients with PAH and 25 patients with CTEPH were studied by measuring conventional markers, GTP-related Rap1 levels, RhoA, RalA, Rac1 and Ras in the platelets." (PMID 36984870, 2023).
Splenomegaly (1 paper, 2023). Abnormal increased size of the spleen. "RalA overexpression significantly promoted splenomegaly in CML mice in terms of volume and weight." (PMID 36923939, 2023).
squamous cell carcinoma (1 paper, 2018). A carcinoma arising from squamous epithelial cells. "The only exception so far is squamous cell carcinoma (SCC), where RalA was found to suppress rather than promote tumor progression." (PMID 30320548, 2018).
tumor (55 papers, 2010 to 2025). "Our analysis of BC patient tumor gene expression using the large METABRIC cohort found that elevated RALA expression was associated with poor outcomes while elevated RALB expression was associated with a more favorable prognosis." (PMID 39272901, 2024). "PP2A dephosphorylation of RalA leads to tumor suppression and loss of RalA regulation, resulting in dysfunctional cell growth, migration, and apoptosis." (PMID 37763671, 2023). "RALA was positively correlated with tumor mutation load (TMB) in BRCA, UCEC, LUAD and THYM (p<0.05), and negatively correlated with TMB in COAD, KIRC, THCA and UVM (p<0.05)." (PMID 36466919, 2022). "Activating RalA would promote the growth of tumor cells, and loss of RalB function inhibited tumor metastasis." (PMID 36499343, 2022). "The results showed that the pathways significantly associated with RALA were mainly cellular response to hypoxia, tumor proliferation signature, EMT markers, ECM related genes, angiogenesis, apoptosis, DNA repair, G2M checkpoint, Inflammatory response." (PMID 36466919, 2022). "Of the two mammalian Ral orthologs, RalA, is associated with tumor initiation and anchorage-independent growth, whereas RalB is associated with invasion, metastasis and survival." (PMID 34071831, 2021). "In KRAS mutated human pancreatic carcinoma cells RALA is found to be necessary for anchorage-independent growth in vitro and for tumor growth in vivo." (PMID 26033452, 2015). "Rap1A and RalA are Ras subfamily members and are associated with endothelial cell adhesion and tumor genesis, respectively." (PMID 23028658, 2012). "We propose that this process occurs during tumor cell migration and invasion, and that Exocyst-association and localization of factors is allosterically regulated by RalA interactions with both Sec5 and Exo84." (PMID 22761837, 2012). "Survival analysis demonstrated that RALA was the sole independent risk factor for poor overall survival and disease-free survival in OS patients and impacted the proportion of infiltrating immune cells and DNA methylation in the OS tumor microenvironment." (PMID 36817861, 2023). "These two observations could be linked, as RalA/B-dependent EVs could promote endothelial permeability locally in the primary tumor or at distance in lungs, thereby favoring both tumor intravasation and extravasation." (PMID 33404012, 2021). "However, they exhibited variability in their ability to bind RALA effector protein, with one showing increased effector binding, as is typically observed in tumor-associated RAS alleles, and the others all reducing effector binding." (PMID 30500825, 2018). "Together, this highlights the importance of RALA in tumor formation for both RAS-dependent MCF7 and RAS-independent MiaPaCa2 cells." (PMID 40568758, 2025). "Since S194 phosphorylation is vital for RALA-dependent tumor formation, targeting this site can have therapeutic advantages." (PMID 40568758, 2025). "While the role of RALA in tumor formation is well established in the literature, how RALA S194 phosphorylation affects tumorigenesis is less clear and more variable." (PMID 40568758, 2025). "Despite the complex nature of its regulation, the need for Serine-194 phosphorylation of RALA to support tumor formation is evident." (PMID 40568758, 2025). "Depletion of either RALA or RALB significantly increased the tumor collagen area relative to shCTRL tumors." (PMID 39272901, 2024). "These in vivo data, along with previously published findings, support a critical role for RALA in TNBC tumor growth and progression as well as a critical role for RALB in some, but not all TNBC models." (PMID 39272901, 2024). "RALA knockout resulted in decreased Ki67 tumor staining while RALB knockout was accompanied by increased Ki67 staining." (PMID 39272901, 2024).
tumor (continued). "RalA knockdown prolonged survival and promoted sensitivity to imatinib in a patient-derived tumor xenograft model." (PMID 36923939, 2023). "Classically, different studies in human cells have shown that RalA is important for tumor cell growth, whereas RalB is important for tumor cell survival and invasiveness." (PMID 35897776, 2022). "The expression level of RALA was predicted by the database to be significantly higher in HCC tumor tissues than in normal tissues and varied by stage." (PMID 36466919, 2022). "It has been proved that RalA plays an essential role in regulating cancer initiation, invasion, migration, and metastasis, which makes it an interesting tumor therapeutic target." (PMID 36092663, 2022). "For instance, RalA is required for anchorage-independent proliferation, whereas RalB is indispensable for survival of tumour cells." (PMID 35879328, 2022). "Despite this, our single-cell RNA sequencing analysis further revealed that the RALA was the tumor-derived endothelial cell marker in LUAD." (PMID 36483553, 2022). "have shown that RALA knockdown inhibits in situ tumor growth in TNBC cells, while RALB knockdown accelerates this process." (PMID 36466919, 2022). "Either paralog was sufficient to sustain tumor growth and only when both RALA and RALB were deleted was tumor formation blocked." (PMID 35626682, 2022). "At the mRNA level, we analyzed the correlation between the mRNA obtained by RALA gene transcription in pan-cancer and the variation of tumor copy number alteration (CNA)." (PMID 36466919, 2022). "We used TISIDB database to analyze the relationship between RALA expression and tumor staging in pan-cancer." (PMID 36466919, 2022). "And, we further found the expression of RALA was specifically upregulated in endothelial cells driven from tumor tissues." (PMID 36483553, 2022). "Overall, our extensive cancer research on RALA showed significant differential expression of this gene between tumor and normal tissues, and elucidated the correlation between RALA expression and immune cell infiltration and common immune checkpoints." (PMID 36466919, 2022). "The activation of Ras small GTPases, including RalA and RalB, plays an important role in carcinogenesis, tumor progress, and metastasis." (PMID 34869198, 2021). "This work examines the potential of RALA, a short amphipathic peptide, to enhance the uptake efficiency of negatively charged AuNPs in tumour cells, detailing the subsequent impact of AuNP internalisation on tumour cell radiation sensitivity." (PMID 34538237, 2021). "With this work, RalA and RalB add to the list of proteins known to control exosome secretion and to affect tumor progression, such as Rab27a, Alix, syntenin, and components of the ESCRT machinery." (PMID 33404012, 2021). "Since on one hand RalA and RalB positively control the levels and the functionality of secreted tumor EVs, and on the other hand they promote metastasis, we tested a direct impact of RalA/B-dependent EVs on the promotion of lung metastasis." (PMID 33404012, 2021). "When compared to the tumor growth rate, the most dramatic reduction of metastasis was observed in the case of RalA depletion." (PMID 33404012, 2021). "First, RalA and RalB have antagonist effects on tumor growth measured in vivo over time and ex vivo after 41 days: while RalA depletion significantly increased tumors growth, RalB depletion induced the opposite effect when compared to control tumors." (PMID 33404012, 2021). "RalGEF is a downstream effector of Ras that activates the Ras family proteins RalA and RalB, which are known to play a role in tumor growth and metastasis; RalA is involved in tumor initiation, whereas RalB is known to promote tumor metastasis." (PMID 31100813, 2019). "More interestingly, both RalB and RalA expression was higher in tumor cells than in normal juxtatumoral cells." (PMID 30320548, 2018).
tumor (continued). "It is suggested that RALGPS2 functions as an inhibitor of RalA signaling and thereby decreases tumor cell proliferation and induces apoptosis." (PMID 27699500, 2017). "Evidence indicates that dephosphorylation of RalA is a major mechanism by which PP2A Aβ normally restricts tumor progression, which appears to be a critical step in the Ras-induced transformation and tumorigenesis of human cells." (PMID 27286458, 2016). "The product of RALA belonged to the oncogene RAS family of proteins and was involved in the MAPK/ERK signal transduction pathway which is the hallmark process of tumor." (PMID 25874214, 2015). "Our results support the function of the RALA pathway as an additional collateral pathway further driving tumor progression." (PMID 26033452, 2015). "The Ral (Ras-like) GTP-binding proteins (RalA and RalB), as effectors of the proto-oncogene Natural killer (NK) cells are an important component of the anti-tumor response." (PMID 25431955, 2014). "In this study we investigated the role of RalA-Exocyst interactions in migration and invasion of tumor cells." (PMID 22761837, 2012). "Here we compared individual impact of RalA and RalB activation on stimulation of tumor growth and metastasis and estimated effect of simultaneous RalA and RalB overexpression on these properties." (PMID 21714887, 2011). "We also presented here the data concerning effect of RalA and RalB on expression, phosphorylation status and activity of various key proteins known to be involved in tumor progression and metastasis." (PMID 21714887, 2011). "Here we compared the influence of constitutively active RalA and RalB expression on tumor progression." (PMID 21714887, 2011). "Earlier, it was suggested that RalA was essential for anchorage-independent growth of transformed cells while RalB was responsible for tumor cell-autonomous survival." (PMID 21714887, 2011). "It was shown that RalA and RalB were necessary for acquisition of aggressive cellular phenotype in diverse models of tumor progression." (PMID 21714887, 2011). "The only known tumor formation study in RALA knockdown pancreatic cancer cells (CFPac-1, HPAC, Capan1) reconstituted with WT-RALA versus S194A-RALA phosphodeficient mutant showed loss of RALA to affect tumor formation that is restored by WT-RALA reconstitution." (PMID 40568758, 2025). "This suggests the RALA S194 phosphorylation is required for tumor formation in these cells." (PMID 40568758, 2025). "They show that RALA S194 phosphorylation is indeed required for RALA-dependent tumor formation." (PMID 40568758, 2025). "Whether AURKA targeting could be an effective way to block RALA-dependent tumor growth is thus a question worth addressing." (PMID 40568758, 2025). "This suggests the tumor formation in MCF7 could be marginally less dependent on RALA S194 phosphorylation." (PMID 40568758, 2025). "The best evaluation of RALA function in cancers stems from its ability to support tumor formation." (PMID 40568758, 2025). "Following our observation that survivorship across BC, and especially in TNBC, is linked to the RALs, we herein explore the requirements of RALA and RALB in supporting cancer cell viability and tumor growth across a panel of BC cell lines with special focus granted to TNBC and HER2+ BC." (PMID 39272901, 2024). "To understand how the loss of RALs in the tumor cells could impact the TME and thereby contribute to decreased tumor growth, we compared the secreted proteomes of the control and RALA or RALB depleted MDA-MB-468 cells." (PMID 39272901, 2024). "Additionally, a Masson’s Trichrome stain of the MDA-MB-468 tumors suggests that loss of either RALA or RALB alters the collagen deposition, which is a phenotype associated with changes in BC tumor metabolism." (PMID 39272901, 2024).